TAF7L (TATA-box binding protein associated factor 7 like)
Description:
Probably functions as a spermatogenesis-specific component of the DNA-binding general transcription factor complex TFIID, a multimeric protein complex that plays a central role in mediating promoter responses to various activators and repressors. May play a role in spermatogenesis (By similarity).
Synonyms: CT40; TAF2Q
Tractability: No criterion of Open Targets' tractability assessment is met for any kind of drug.
Gene: Protein-coding gene on chromosome X (101,268,253 to 101,293,057, reverse strand). Ensembl gene ENSG00000102387.
Subcellular location: Nucleus; Cytoplasm
Subcellular location (Human Protein Atlas): Nucleoplasm; Cytosol
Pathways (Reactome):
Gene expression (Transcription): RNA Polymerase II Pre-transcription Events; RNA Polymerase II Promoter Escape; RNA Polymerase II Transcription Initiation; RNA Polymerase II Transcription Initiation And Promoter Clearance; RNA Polymerase II Transcription Pre-Initiation And Promoter Opening
Disease: HIV Transcription Initiation; RNA Polymerase II HIV Promoter Escape; Transcription of the HIV genome
Gene Ontology:
Molecular function: protein binding; RNA polymerase II general transcription initiation factor activity
Biological process: RNA polymerase II preinitiation complex assembly; transcription initiation at RNA polymerase II promoter
Cellular component: transcription factor TFIID complex; cytoplasm; nucleus
Homologues: Orthologues: chimpanzee TAF7L (96% identical), macaque TAF7L (90% identical), pig TAF7L (73% identical), dog TAF7L (71% identical), rat Taf7l-ps1 (62% identical), mouse Taf7l2 (58% identical), mouse Taf7l (57% identical), rat Taf7l (57% identical), guinea pig TAF7L (56% identical), rabbit TAF7L (52% identical), Drosophila melanogaster Taf7 (32% identical), Caenorhabditis elegans taf-7.2 (20% identical), and 1 more. Paralogues in human: TAF7 (56% identical).
Diseases named in the same sentence as TAF7L in open-access papers:
TAF7L is named in the same sentence as 10 diseases in open-access papers, as found by Europe PMC text mining. Sharing a sentence is not in itself a finding about the gene and the disease. The quoted sentences say what the papers report.
breast carcinoma (3 papers, 2022 to 2023). "TAF7L has been shown to be upregulated and involved in breast cancer development." (PMID 37835379, 2023). "TAF7L was previously suggested for its role in the tumorigenesis of breast cancer." (PMID 37835379, 2023). "The CT genes, OIP5, TAF7L, and AURKC have been identified as biomarkers for breast cancer and may be promising and potent candidates for therapeutic cancer vaccines." (PMID 36967804, 2023).
male infertility (3 papers, 2013 to 2023). The inability of the male to effect fertilization of an ovum after a specified period of unprotected intercourse. "Another X-linked gene, TAF7L (also known as CT40), was linked to OAT and male infertility in the current study, and four X-linked hemizygous deleterious variations of TAF7L were detected in probands, but with significantly reduced in vitro fertilization." (PMID 36714566, 2022). "However, further investigation will be required to assess whether there are more direct links between adipogenesis and spermatogenesis and whether mutant Taf7l involved in male infertility also disturbs normal fat development and metabolism." (PMID 23326641, 2013). "It has also been proved that taf7l, as a paralogue of taf7 (transcription initiation factor TFIID subunit 7), cooperates with trf2 to regulate spermiogenesis, and the variation of taf7 affects the genetic etiology of idiopathic male infertility." (PMID 37645057, 2023).
head and neck cancer (1 paper, 2024). A primary or metastatic malignant neoplasm affecting the head and neck. "There has been previous evidence of differential expression of e.g. NEFH, ZRF2,TAF7L, ZNF541 and TYMS in head and neck cancer, related to HPV status." (PMID 38643268, 2024).
Infertility (1 paper, 2021). "Moreover, a point mutation of human TAF7L is associated with infertility." (PMID 34237055, 2021).
lung carcinoma (1 paper, 2024). "These genes include GRIA3, TAF7L, ARL14, PCDHGA9, MDGA1, ZFPM2, OSR2, TMC8/TMC6, HCN2, and CDK5R2, which are likely to be relevant in human lung cancer and are also epigenetically deregulated upon exposure to ECS in our animal study." (PMID 39273313, 2024).
Obesity (1 paper, 2013). Accumulation of substantial excess body fat. "It is conceivable that TAF7L and associated regulatory factors in this newly discovered pathway may reveal potentially useful therapeutic drug targets to combat obesity and its related diseases." (PMID 23326641, 2013).
cancer (3 papers, 2021 to 2023). A tumor composed of atypical neoplastic, often pleomorphic cells that invade other tissues. "In particular, SYCP2 and TAF7L, which have been shown in the past to be deregulated in cancer development." (PMID 36142875, 2022). "TAF7L is also classified as a cancer-testis antigen (CTAg), belonging to a group of genes typically expressed only in the germline but also in malignant tumours." (PMID 34215292, 2021).
tumour (2 papers, 2021 to 2024). "A small number of genes were found significantly differentially expressed in HPV-positive versus HPV-negative tumours (for example NEFH, ZFR2, TAF7L, ZNF541, and TYMS)." (PMID 38643268, 2024).
TAF7L also shares sentences with these, for which no sentence is quoted: acute myeloid leukemia (1 paper); X-linked agammaglobulinemia (1).